RN7SL711P (RNA, 7SL, cytoplasmic 711, pseudogene)
Gene: Miscellaneous RNA gene on chromosome 5 (123,070,782 to 123,071,080, forward strand). Ensembl gene ENSG00000276047.
Homologues: Orthologues: chimpanzee Metazoa_SRP (99% identical), macaque Metazoa_SRP (92% identical), rat Metazoa_SRP (32% identical). Paralogues in human: RN7SL1 (86% identical), RN7SL2 (86% identical), RN7SL3 (84% identical), RN7SL655P (84% identical), RN7SL296P (81% identical), RN7SL147P (81% identical), RN7SL398P (81% identical), RN7SL712P (80% identical), RN7SL126P (80% identical), RN7SL543P (80% identical), RN7SL145P (80% identical), RN7SL448P (80% identical), and 702 more.